FCGR3A (Fc gamma receptor IIIa)
Diseases named in the same sentence as FCGR3A in open-access papers (continued):
Sharing a sentence is not in itself a finding about the gene and the disease.
sarcoidosis (5 papers, 2017 to 2025). Sarcoidosis is a multisystemic disorder of unknown cause characterized by the formation of immune granulomas in involved organs. "The analysis of the FCGR3A gene polymorphism was the most promising for finding a distinction between the immune response mechanisms, present in sarcoidosis and tuberculosis, due to the previously revealed increase in the percentage of blood monocytes with FcγRIII in SA versus TB." (PMID 37174624, 2023). "Therefore, we have analyzed polymorphism of these genes in our SA patients and revealed that, in contrast to polymorphism of FCGR2B and FCGR3B, polymorphism of FCGR2A, FCGR2C and FCGR3A may contribute to immunocomplexemia present in sarcoidosis." (PMID 28472129, 2017). "We have found a lack of association between copy number of FCGR2A, FCGR2B, FCGR2C, FCGR3A, FCGR3B genes and risk of development of sarcoidosis in our patients." (PMID 28472129, 2017). "Similar to NL and NXG, sarcoidosis lesional macrophages upregulated expression of the macrophage polarization marker genes MARCO, FCGR3A, NR1H3; the ECM-encoding gene FN1; the protease-encoding gene CTSS; and genes associated with inflammation, S100A8 and CHI3L1." (PMID 39989459, 2025). "This can explain the presence of immunocomplexemia in the blood of our patients suffering from sarcoidosis, as the 158F variant of FCGR3A gene results in the forming of CD16A receptor with a lower IC binding ability than the receptor coded by the 158V variant of FCGR3A gene." (PMID 37298666, 2023). "CNV of FCGR3A gene occurred in 13.46% of SA patients and 18.18% of healthy controls, whereas CNV of FCGR3B gene was present in 29.13% of patients with sarcoidosis and in 22.43% of the controls." (PMID 28472129, 2017).
atherosclerosis (4 papers, 2017 to 2025). A disease characterized by the build-up of fatty material and calcium deposition in the arterial wall resulting in partial or complete occlusion of the arterial lumen. "FCGR3A is also named as CD16 which has been identified as the pathogenic factor to participate in the deterioration of atherosclerosis, and the study has indicated that FCGR3A may be connected with ischemic stroke." (PMID 35070236, 2022). "The literature suggested FCGR3A(CD16A) + monocytes were significantly increased in apoE-/- mice with high fat diet, which might correlate with aortic MMP-9 mRNA expression and serum TNF-α level, indicaitng FCGR3A involved in the progression of atherosclerosis through inflammatory pathways." (PMID 41348730, 2025).
diffuse large B-cell lymphoma (4 papers, 2022 to 2024). "It is worth noting that all cholangiocarcinoma cases, liver hepatocellular carcinoma cases, pancreatic adenocarcinoma cases, pheochromocytoma, paraganglioma cases, and diffuse large B-cell lymphoma with genetic alteration (>2% frequency) had copy number amplification of FCGR3A." (PMID 39280892, 2022). "All cholangiocarcinoma, liver hepatocellular carcinoma, pancreatic adenocarcinoma pheochromocytoma and paraganglioma, diffuse large B-cell lymphoma, ovarian serous cystadenocarcinoma, thymoma, and mesothelioma cases with genetic alteration had FCGR3A amplification." (PMID 35668930, 2022). "The study found that FCGR3A gene polymorphisms may correlate with response to frontline rituximab plus cyclophosphamide/doxorubicin/vincristine/prednisone (R–CHOP) with diffuse large B-cell lymphoma (DLBCL)." (PMID 39280892, 2022).
glioblastoma (4 papers, 2014 to 2024). The most malignant astrocytic tumor (WHO grade IV). "In addition, high FCGR3A expression was associated with poorer disease-free survival (DFS) in esophageal carcinoma (ESCA), glioblastoma multiforme (GBM), LGG, and prostate adenocarcinoma (PRAD)." (PMID 39280892, 2022). "FCGR3A and FGL2 are highly expressed in elderly individuals, glioblastoma patients (G4), those with tumor progression after initial treatment, and those with poor prognosis confirmed by OS, DSS and PDI." (PMID 39629005, 2024). "We noted an overlap of up-regulated genes with an immune signature reported in a glioblastoma profiling study, including MHC class I and II genes, the complement factors C1QA/B/C, FCGR3A, B2M, SOCS3, TLR2 and CTSH." (PMID 25593989, 2014).
neuroblastoma (4 papers, 2021 to 2024). Neuroblastoma (NB) is the most common solid, extracranial childhood tumor. "Notably, TAMs in high-risk neuroblastoma tissues highly expressed the macrophage-activating Fcγ receptor genes FCGR2A and FCGR3A, and therefore, antibody-mediated approaches are plausible for treating high-risk neuroblastoma patients." (PMID 38920727, 2024). "In addition, among Fcγ receptor genes, FCGR2A and FCGR3A, encoding activating receptors, are expressed at relatively high levels in high-risk neuroblastoma tissues, suggesting the potential roles of these FCGRs in macrophage-mediated anti-high-risk neuroblastoma immunity." (PMID 35525858, 2022). "In contrast to the LTI study, in our cohort, haplo HSCT using donors with high affinity FcGR3A or FcGR2A did not have any impact on event-free survival and overall survival in neuroblastoma Stage IV relapsed patients with subsequent GD2 targeted ch14.18/CHO antibody therapy." (PMID 34367149, 2021).
prostate carcinoma (4 papers, 2017 to 2024). A carcinoma that arises from epithelial cells of the prostate gland. "FCGR3A is the target of many drugs such as rituximab and its expression in prostate cancer cells is positively correlated with other markers." (PMID 36505767, 2022).
renal clear cell carcinoma (4 papers, 2022). "In tumor tissue samples from patients with clear cell renal cancer, the predominant production of the FCGR3A mRNA was observed in comparison with the FCGR3B mRNA." (PMID 37064811, 2022). "FCGR3A (Fc fragment of IgG receptor IIIa) encodes the receptor for the Fc region of immunoglobulin G. FCGR3A interacts with FCGR1A in numerous pathophysiological processes and is substantially related with overall survival (OS) in CM, renal clear cell carcinoma, and other malignancies." (PMID 35957907, 2022). "The existing evidence that FCG1A is positively correlated with immune infiltration levels of various cancers, especially cervical cancer (CESC), cholangiocarcinoma (CHOL), renal clear cell carcinoma (KIRC), and skin melanoma may help us to infer the correlation between FCGR3A and cancer." (PMID 39280892, 2022).
tuberculosis (4 papers, 2023). A chronic, recurrent infection caused by the bacterium Mycobacterium tuberculosis. "In addition, phagosome processes and tuberculosis disease were also significantly enriched, and AKT3, CD14, FCGR3A, and CORO1A were significantly up-regulated in the MAB group." (PMID 37764178, 2023). "Interestingly, phagosome processes and tuberculosis disease were also significantly enriched, with AKT3, CD14, FCGR3A, and CORO1A being significantly up-regulated in MAB-infected patients." (PMID 37764178, 2023).
Crohn disease (3 papers, 2021 to 2024). A gastrointestinal disorder characterized by chronic inflammation involving all layers of the intestinal wall, noncaseating granulomas affecting the intestinal wall and regional lymph nodes, and transmural fibrosis. "Our findings suggest that FCGR3A may play a role in the pathogenesis of pediatric Crohn’s disease, potentially through its involvement in immune responses and inflammation." (PMID 36936436, 2023). "Gene FCGR3A—upregulated in three of the CVD tissues (Brain – Spinal cord adj.P.val = 0.02; Brain – Caudate adj.P.val = 0.03; Artery – Tibial adj.P.val = 0.02)—encodes a receptor that binds the Fc portion of IgG, and it affects the pharmacokinetics in patients with Crohn’s Disease." (PMID 34349785, 2021).
inflammatory bowel disease (3 papers, 2016 to 2022). A spectrum of small and large bowel inflammatory diseases of unknown etiology. "In fact, the genetic amino acid substitution p.V158F (rs396991) in the FCGR3A gene, which is well described in the literature, was found to affect the response to antibodies treatment in the case of inflammatory bowel disease." (PMID 32922288, 2020).
staphylococcus aureus infection (3 papers, 2020 to 2022). An infectious process in which the bacteria Staphylococcus aureus is present. "Gene FCGR1A, FCGR3A, and FCGR3B were enriched in both the staphylococcus aureus infection and osteoclast differentiation pathways, and belong to the Fc gamma receptor (FcγR), a receptor for the Fc portion of IgG." (PMID 33344459, 2020). "Then, LYN, FCGR3A, and FCGR3B are involved in “module 1” of the subnetwork, in which GO functional annotation is enriched in inflammatory response and immune response, and KEGG pathway enrichment analysis is enriched in staphylococcus aureus infection, phagosome, and osteoclast differentiation." (PMID 32733557, 2020).
Stroke (3 papers, 2012 to 2025). Sudden impairment of blood flow to a part of the brain due to occlusion or rupture of an artery to the brain. "Of these, Fcgr2b, Fcgr3a, and Tnfrsf26 also displayed a strong age effect, being more strongly upregulated early after stroke in aged (2- to 3-fold) than in young rats." (PMID 23251410, 2012). "Aged rats, on the contrary, had early post-stroke increases in expression of phagocytosis-promoting genes like Fcgr2b and Fcgr3a, and for the pro-apoptotic acting gene, tumor necrosis factor receptor superfamily, member 26 (Tnfrsf26)." (PMID 23251410, 2012).
Takayasu arteritis (3 papers, 2015 to 2018). A rare inflammatory large-vessel vasculitis primarily affecting the aorta and its major branches, but also other large vessels, causing stenosis, occlusion, or aneurysm. "In CD8+ cells, two transcripts remained differentially expressed after 12 months; SGTB, associated with neuronal apoptosis, and FCGR3A, associatied with Takayasu arteritis." (PMID 30037347, 2018). "A recent genome-wide association study revealed that the FCGR2A/FCGR3A genes confer susceptibility to Takayasu arteritis, another chronic large-vessel vasculitis." (PMID 30037347, 2018). "The same study also suggested a link between Takayasu arteritis and the FCGR2A/FCGR3A locus." (PMID 26839728, 2015).
ulcerative colitis (3 papers, 2017 to 2022). An inflammatory bowel disease involving the mucosal surface of the large intestine and rectum. "Results of our present study are also in agreement with the lack of association between CNV of FCGR3A gene and etiology of ulcerative colitis, Kawasaki disease, RA in Caucasian population of the United Kingdom, as well as Caucasian and Chinese patients with SLE." (PMID 28472129, 2017).
asthma (2 papers, 2014 to 2023). "We again investigated the 24 drugs in Drug Bank and CheMBL, and confirmed that FCGR3A was associated with six asthma drugs that were approved or under clinical trials." (PMID 37875944, 2023). "Among the 9 colocalization genes specific to Korean asthma, FCGR3A is well known for its association with various innate immune responses, and has been reported to interact with certain approved asthma drugs." (PMID 37875944, 2023). "Of all the asthma-related genes, only FCGR3A (Fc gamma receptor IIIa) was found to interact with 24 drugs." (PMID 37875944, 2023). "Third, through the drug target analysis, we discovered that the FCGR3A gene interacts with asthma drugs that have either been approved or are currently undergoing clinical trials." (PMID 37875944, 2023). "Additionally, three asthma drugs undergoing clinical trials were found to interact with FCGR3A, despite targeting TNF (adalimumab and etanercept) and PTGS1/PTGS2 (indomethacin)." (PMID 37875944, 2023).
bladder cancer (2 papers, 2022 to 2025). "Consistent with that notion, blood NK cells expresse more FCGR3A mRNA, the gene that encodes CD16a, than tumor-infiltrating NK cells in bladder cancer and that was driven by transforming growth factor receptor β47." (PMID 41219228, 2025). "This is similar to FCGR3A in other tumor models, for example, the level of natural killing activity in peripheral blood mononuclear cells of patients with bladder cancer is correlated with the clinical evolution and pathological stage of the disease." (PMID 36505767, 2022).
chronic GVHD (2 papers, 2024 to 2025). "Additionally, the V158F polymorphism within the FCGR3A gene has been identified as a potential predictor of outcomes in bone marrow transplantation, with the V/V genotype associated with a reduced risk of both acute and chronic GVHD as well as improved overall survival rate." (PMID 40433377, 2025). "We found weak genetic associations between polymorphisms in the CD226, CD244, FCGR3A, KLRD1, NCR3, and PVRIG genes, and the risks for relapse, acute GVHD, and chronic GVHD in the HSCT discovery cohort but not in the replication cohort." (PMID 39506082, 2024).
co-infection (2 papers, 2013 to 2017). "In this study we investigated whether copy number variation of FCGR2C, FCGR3A and FCGR3B as well as HNA1 allelic variation of FCGR3B is associated with HIV load, response to HAART and co-infection with TB in two African populations." (PMID 24250791, 2013). "In this study we investigated whether CNV of FCGR2C, FCGR3A and FCGR3B as well as the HNA1 allotype of FCGR3B is associated with HIV load, response to highly-active antiretroviral therapy (HAART) and co-infection with TB." (PMID 24250791, 2013).
cytomegalovirus infection (2 papers, 2025). A herpesvirus infection caused by Cytomegalovirus. "Genetic syndromes such as GATA2 deficiency or mutations in genes that lead to loss of CD16 (MCM4 and FCGR3A) have been linked to impaired NK cell development and function and are commonly associated with severe or atypical HCMV infections." (PMID 40732677, 2025). "In the present study, we identified a unique case of a GBS patient with a preceding cytomegalovirus infection who had three copies of parts of FCGR3A and FCGR3B, along with three copies of the entire FCGR2C and HSPA7 genes." (PMID 40593358, 2025). "One patient, with a preceding cytomegalovirus infection, was identified with three copies of parts of both FCGR3A and FCGR3B and three copies of the entire FCGR2C and HSPA7 genes, suggestive of a novel CNR (CNR5)." (PMID 40593358, 2025).
esophageal cancer (2 papers, 2020 to 2022). A primary or metastatic malignant neoplasm involving the esophagus. "This analysis revealed that PRAD, liver hepacellular carcinoma (LIHC) and esophagus carcinoma (ESCA) as the cancer types with the lowest FCGR3A gene expression." (PMID 31991588, 2020).
giant cell arteritis (2 papers, 2006 to 2017). "In addition, a genetic association between the FCGR2A/FCGR3A polymorphism and giant cell arteritis (GCA) has been previously identified in a small cohort from Spain." (PMID 27769046, 2017).
lung squamous cell carcinoma (2 papers, 2022). "Meanwhile, a lower expression of FCGR3A was found in adrenocortical carcinoma (ACC) and lung squamous cell carcinoma (LUSC) dataset." (PMID 35668930, 2022).
lupus nephritis (2 papers, 2012 to 2025). Glomerulonephritis in the context of systemic lupus erythematosus. "We conducted a detailed analysis of the association between FCGR2A, FCGR2B, FCGR3A and FCGR3B polymorphisms and lupus nephritis." (PMID 40728959, 2025). "This is exemplified by the FCGR3A V158F polymorphism that is associated with lupus nephritis, but not with SLE susceptibility overall." (PMID 23049788, 2012).
neutropenia (2 papers, 2013 to 2025). A decrease in the number of neutrophils found in the blood. "To focus on the relationship between the FCGR3A polymorphism and RTx-induced LON, we excluded cases of neutropenia during CMV infection from the definition of LON in this study." (PMID 39804516, 2025). "However, the authors did report that FCGR3A polymorphisms were associated with the rate of grade 3–4 neutropenia during induction therapy consistent with previous reports that immune mechanisms mediated by NK cells may play a role in rituximab-induced neutropenia." (PMID 23286345, 2013). "This study has 2 main limitations: 1) we did not include KTx recipients who did not receive RTx induction therapy, so it remains unclear whether FCGR3A polymorphisms influence neutropenia risk during CMV infection without RTx." (PMID 39804516, 2025).
osteosarcoma (2 papers, 2023 to 2024). A usually aggressive malignant bone-forming mesenchymal neoplasm, predominantly affecting adolescents and young adults. "Besides, expression of UNC5B, CAM1, PTH1R, and FCGR3A was significantly associated with survival of patients with osteosarcoma." (PMID 37457661, 2023). "Our findings revealed a consistent prevalence of CD16high subgroups, characterized by FCGR3A expression, within the osteosarcoma microenvironment both before and after chemotherapy." (PMID 39033089, 2024).
Pan (2 papers, 2022 to 2024). "Pan cancer analysis confirms this hypothesis that changed expression of FCGR3A and FGL2 occurs in most tumor types." (PMID 39629005, 2024).
pancreatic cancer (2 papers, 2018 to 2024). "In pancreatic cancer, FCGR3A is linked to tumor growth, metastasis, and infiltration of M2 macrophages." (PMID 39574475, 2024). "Through public database analysis, tissue immunofluorescence, and in vitro cell experiments, we identified that FCGR3A is associated with M2 macrophage infiltration or polarization and contributes to pancreatic cancer proliferation and metastasis." (PMID 39574475, 2024). "In this study, an M2 macrophage-related pancreatic cancer risk score model was established, and found that FCGR3A was correlated with tumor formation, metastasis, and M2 macrophage infiltration." (PMID 39574475, 2024). "Furthermore, cell experiments confirmed that FCGR3A is related to M2 macrophage polarization, as well as pancreatic cancer proliferation and development." (PMID 39574475, 2024). "Moreover, in vitro cell experiments were conducted, where FCGR3A was knocked down in pancreatic cancer cells using siRNA to analyze its effects on M2 macrophage infiltration, tumor proliferation, and metastasis." (PMID 39574475, 2024). "Furthermore, FCGR3A knockdown significantly lowered the potential of pancreatic tumor cells to spread, as shown by transwell and wound healing studies." (PMID 39574475, 2024). "However, the prognostic significance of FCGR3A expression in pancreatic cancer and its correlation with immune infiltration remains unclear." (PMID 39574475, 2024). "Thus, FCGR3A could serve as a potential therapeutic target in pancreatic cancer." (PMID 39574475, 2024). "When compared to normal pancreatic ductal epithelial cells (HPNE), we first observed that pancreatic tumor lineages (PANC-1, CAPAN-2, and BXPC-3) had significantly higher expression levels of FCGR3A." (PMID 39574475, 2024).
prostate adenocarcinoma (2 papers, 2022). "It was noteworthy that there was a certain proportion of FCGR3A copy number deletion in stomach adenocarcinoma, prostate adenocarcinoma, and kidney renal papillary cell carcinoma." (PMID 35668930, 2022).